TRIM21 (tripartite motif containing 21)
Diseases named in the same sentence as TRIM21 in open-access papers (continued):
Sharing a sentence is not in itself a finding about the gene and the disease.
tumor (continued). "For instance, tripartite motif containing 21 (TRIM21) which has E3 ligase activity and functions in the process of ubiquitination and is a potential tumor suppressor in HCC." (PMID 29027943, 2017). "This was confirmed by western blots for Oct-1, TRIM21, ALDH and SAE2 in the mice tumour tissues from in vivo LDA." (PMID 27465491, 2016). "Given our findings, TRIM21-based PROTACs may be developed specifically degrade ID1 in PAAD, especially in hypoxic tumor areas where malignancy is driven by ID1 stability." (PMID 40919143, 2025). "Additionally, TRIM21-mediated METTL3 degradation induces ferroptosis by disrupting SLC7A11 mRNA stability and inhibits tumor progression during anti–PD-1 therapy." (PMID 40175350, 2025). "To verify whether TRIM21 acts its tumor suppressor function via PRMT1, we overexpressed PRMT1 in CRC cells with a base of TRIM21 overexpression." (PMID 39890802, 2025). "Tumors arising from HCT116 cells with TRIM21 knockdown had significant slower tumor growth than those without TRIM21 knockdown, and treatment with 5-FU further restrained tumor growth." (PMID 40998798, 2025). "In CRC, TRIM21 could enhance Cisplatin resistance of tumor cells by down-regulating PAR4 and promote tumor growth in nude mice." (PMID 40998798, 2025). "Finally, Trim21 knockdown inhibited the therapeutic effect of LNP-pE285K-mAb, as evidenced by tumor volumes (7 J and K) and animal survival." (PMID 38886748, 2024). "When MDA‐MB‐231EV, MDA‐MB‐231CCT6A, MDA‐MB‐231CCT6A+TRIM21 or MDA‐MB‐231CCT6A+TRIM21‐ΔRING cells were injected into nude mice, compared with MDA‐MB‐231CCT6A cells, MDA‐MB‐231CCT6A+TRIM21 cells presented significantly reduced tumour weight and tumour volume." (PMID 39556022, 2024). "Furthermore, TRIM21 was reported to be highly expressed in immune cells, such as B cells, CD4 + T cells, macrophages, neutrophils, and dendritic cells, through the Tumor Immune Estimation Resource (TIMER) database." (PMID 36694250, 2023). "Different from all the other animal studies, Liu showed that propofol could enhance tumor cell adhesion and extension through GABAAR to downregulate TRIM21 expression, leading to the upregulation of Src, a protein associated with cell adhesion." (PMID 37345096, 2023). "CIBERSORTx analysis further confirmed that NPC tumours with higher TRIM21 expression contained fewer infiltrated CD8+ T cells and activated DCs, suggesting that TRIM21 may play a vital role in suppressing T-cell-mediated antitumour immunity." (PMID 36797289, 2023). "What is more, the tumor-promoting effects of DLGAP1-AS2 by inhibiting ELOA were observed in WT but not in Trim21-KO CRC cells." (PMID 36376892, 2022). "Despite the fact that TRIM21 has effects on multiple metabolic processes, inflammatory responses and the efficacy of tumor therapy, there has been no systematic review of these topics." (PMID 36159815, 2022). "Recent reports have shown that TRIM21 participates in the regulation of immune cell subset differentiation; however, its effect on tumor cell differentiation has not been uncovered." (PMID 33414451, 2021). "Mechanistically, propofol could promote tumor metastasis by enhancing tumor cell adhesion and extension via interactions of GABAAR, TRIM21, and Src." (PMID 34263559, 2021). "Our analysis demonstrated that the TRIM21 expression levels are negatively correlated with PI3K activity in various human cancers, implying that TRIM21 may act as a potential tumor suppressor." (PMID 32312982, 2020). "TRIM21 depletion in GBM enhanced cell proliferation and tumor growth." (PMID 33193404, 2020). "More than half of the TRIM21-KO tumours (8/15, 53.3%) completely regressed, and none recurred." (PMID 36797289, 2023).
tumor (continued). "Importantly, Akt can directly phosphorylate PFKP at S386, which prevents the interaction of PFKP with E3 ligase TRIM21 and the subsequent TRIM21-mediated polyubiquitination and degradation of PFKP, resulting in increased PFKP expression, aerobic glycolysis, cell proliferation, and tumor growth." (PMID 40612109, 2025). "However, TRIM21 expression had no significant impact on other clinical characteristics such as age (RR = 1.06; 95% CI: 0.91–1.25; P = .068), sex (RR = 1.04; 95% CI: 0.95–1.12; P = .953), or tumor size (RR = 1.14; 95% CI: 0.97–1.33; P = .05)." (PMID 37335642, 2023). "In CRC tumour tissue, CSN6 and TRIM21 showed a significant negative correlation in staining intensity, while CSN6 and ALDH1A1 showed a significant positive correlation in staining intensity." (PMID 32225170, 2020). "The percentage of GFP-positive cells increased significantly after radiation, while this increase was abrogated in the cells without TRIM21, indicating that SERPINB5-mediated tumor cell radioresistance is dependent on TRIM21." (PMID 32005234, 2020). "Also, anti-Ro52/TRIM21 has been detected in nonautoimmune conditions such as infections and neoplastic diseases." (PMID 24294139, 2013).
cancer (103 papers, 2014 to 2025). A tumor composed of atypical neoplastic, often pleomorphic cells that invade other tissues. "TRIM21 is implicated in both cancer progression and suppression, primarily through K48-linked proteasomal degradation." (PMID 40371639, 2025). "Further studies are required to fully characterize the complex regulation of TRIM21 in different cancer contexts and to dissect its underlying mechanisms." (PMID 40735642, 2025). "The pathophysiologic mechanisms by which SLE and pSS patients have a greater risk of certain cancers have yet to be well understood, and the comprehension of the regulatory role of TRIM21/Ro52 in these diseases and malignancies remains partial." (PMID 37993883, 2023). "TRIM21 was originally implicated in innate immunity, autoimmune responses, and cancer; however, recent studies have suggested a role in cancer metabolism through ubiquitination and degradation of enzymes and signaling regulators." (PMID 37937648, 2023). "TRIM21 showed a significant association with the inhibition of DNA damage response pathways among 16 types of cancer." (PMID 37864041, 2023). "The results showed that high levels of TRIM21 expression were significantly associated with better prognosis in patients with reproductive tumors or other cancers, but worse OS with digestive system cancers." (PMID 37335642, 2023). "TRIM21 also mediates K63-linked ubiquitination in cancer cells." (PMID 40371639, 2025). "TRIM21 is a RING finger E3 ubiquitin ligase that is implicated in a variety of cancer mechanisms." (PMID 40371639, 2025). "Recent evidence has implicated TRIM21 in various activities in cancers." (PMID 40605974, 2025). "In addition to the diagnostic role in SLE and pSS, TRIM21/Ro52 can have opposing effects in different cancers." (PMID 37993883, 2023). "The underlying mechanism of how TRIM21/Ro52 may lead to cancer development or provide a protective effect against cancer in SLE and pSS patients requires further studies." (PMID 37993883, 2023). "Herein, we discuss the emerging role and function of TRIM21 in cancer metabolism, immunity, especially the immune response to inflammation associated with tumorigenesis, and also the cancer treatment, hoping to shine a light on the great potential of targeting TRIM21 as a therapeutic target." (PMID 36159815, 2022). "Similarly to the cancer studies, TRIM21 deficiency has been explored as a potential driver of SLE, by altering B cell regulation." (PMID 34552597, 2021). "However, evidences have revealed that the TRIM21 is also associated with a large number of human cancers." (PMID 32678213, 2020). "Furthermore, downregulation of several E3 ubiquitin ligases such as TRIM21 have been reported in cancer and could highlight how the loss of such proteins could offer an additional approach through which cancer increases glycolysis." (PMID 38201444, 2023). "Further investigation is needed to uncover the mechanisms by which TRIM21/Ro52 contributes to cancer’s progression or offers protective effects against cancer in patients with SLE and pSS." (PMID 40429494, 2025). "PTEN-null cancer cells can directly act on TRIM21 and inhibit its activity to rewire the cancer metabolism by stabilizing the G6P enzyme." (PMID 39851497, 2025). "Accumulating studies have shown that TRIM21 positively and negatively regulate carcinogenesis in different context of cancers." (PMID 40735642, 2025). "In this section, we focused on the role of TRIM21 in the regulation of immune evasion in different context of cancers." (PMID 40735642, 2025). "TRIM21, an antibody-binding protein involved in regulating type-I interferon responses, plays complex roles in cancer." (PMID 40768895, 2025).
cancer (continued). "The substrates of TRIM21 included cytoplasmic and nuclear proteins, and its roles in other cancers had been studied." (PMID 41288005, 2025). "Here, we will review the biological role of TRIM21 in human malignancies and discuss possible therapeutic interventions targeting TRIM21 for cancer treatment." (PMID 40735642, 2025). "Emerging evidence also suggests the involvement of TRIM21 in tumorigenesis, with a dual function in either promoting or suppressing cancer progression depending on cancer types and context." (PMID 40096176, 2025). "This regulatory axis demonstrates the critical role of TRIM21 in modulating cancer metabolism through post-translational control of metabolic transcription factors." (PMID 40735642, 2025). "While TRIM21 has been reported to be involved in various important cellular activities in cancer cells, such as cell metabolism, cytokinesis, and redox regulation, it also contributes to the inhibition of proinflammatory activity in immune cells." (PMID 39152265, 2024). "In cancer cells that have increased PI3K activation (e.g. PTEN mutation), the negative regulators TRIM21 (tripartite motif-containing protein 21) and PHLDA3 are suppressed, thus enhancing the PPP and cell proliferation." (PMID 38270460, 2024). "TRIM21 is involved in the progression of cancers, mainly metabolism, immune regulation, and cancer therapy." (PMID 39154024, 2024). "TRIM21 has the ability to regulate the degradation of Oct‐1, which in turn makes cancer stem cells more responsive to chemoradiation treatment." (PMID 38327131, 2024). "Intriguingly, TRIM21 negatively regulates glucose metabolism in human cancers by modulating the degradation of regulators to promote the dysregulation of glycolysis, for example, promoting the degradation of PFKP and G6PD." (PMID 38092733, 2023). "TRIM21 /Ro52 also features anti-cancer and carcinogenic functions according to different malignancies." (PMID 37993883, 2023). "The autoubiquitination of E3 ligase TRIM21 at K214 and K217 is promoted by the regulator CSN6, thereby decreasing TRIM21-mediated ubiquitination and degradation of Oct1, a transcription activator of another cancer stemness marker ALDH1A1." (PMID 38104139, 2023). "Previous studies of TRIM21 have mainly focused on its participation in cancer and autoimmune diseases." (PMID 37249651, 2023). "More clinical studies should be carried out to get a more accurate evaluation of the prognostic role of TRIM21 in patients with cancers." (PMID 37335642, 2023). "As the research further develops, an increasing number of studies have manifested that the TRIM21 expression level can be considered an indicator of cancer prognosis." (PMID 37335642, 2023). "Cancer cells are intrinsically more susceptible to ferroptosis due to their iron and lipid hypermetabolism and higher ROS levels compared to normal cells; thus, we hypothesized that cancer cells could upregulate TRIM21 under conditions of high oxidative stress." (PMID 37587773, 2023). "Tripartite motif containing-21 (TRIM21) is one of the TRIM family members that has been investigated in various types of cancer." (PMID 37864041, 2023). "TRIM21 plays a paradoxical role in tumourigenesis and the progression of different types of cancers." (PMID 36797289, 2023). "The emerging critical role of TRIM family proteins, including TRIM21, in human cancers suggests the potential application of these proteins in cancer therapies." (PMID 36749630, 2023). "Our meta-analysis comprehensively and systematically reviewed the prognostic value of TRIM21 in various cancers." (PMID 37335642, 2023). "TRIM21 is a ubiquitin E3 ligase that contains the ring finger domain and plays an important role in cancer progression." (PMID 37460470, 2023).
cancer (continued). "Tripartite motif containing 21 (TRIM21) was first discovered for its antiviral function in innate immunity but has recently attracted increasing attention in cancer metabolism and tumorigenesis." (PMID 37422473, 2023). "Our study indicated that TRIM21 was further upregulated upon ferroptosis induction in cancer cells and PDAC mouse models." (PMID 37587773, 2023). "Our study reveals that cancer cells respond to and inhibit ferroptosis by upregulating TRIM21 to promote FSP1 membrane translocation and FSP1 function through K63 ubiquitination." (PMID 37587773, 2023). "TRIM21 acts at multiple nodes to control cancer metabolic reprogramming by inhibiting the increased metabolic demand of malignancy." (PMID 36694250, 2023). "TRIM21 inhibits cancer progression generally through metabolic reprogramming of cancer cells in vitro." (PMID 36159815, 2022). "As a ubiquitination-related molecule, TRIM21 suppresses cancer progression by degrading various oncoproteins." (PMID 35662245, 2022). "Previously studies had showed that TRIM21 expression was decreased in several cancers at both the mRNA and protein levels in comparison to that in nontumorous tissues." (PMID 35662245, 2022). "Due to the complexity of the TME in vivo, the function of TRIM21 varies according to the carcinogenic effectors and the cancer types." (PMID 36159815, 2022). "TRIM21 silencing promotes cancer cell proliferation, migration, and the ability of anti-apoptosis and regulates epithelial carcinogenesis." (PMID 35662245, 2022). "Recently studies have reported that TRIM21 plays a dual role in cancer promoting and suppressing in the occurrence and development of various cancers." (PMID 36159815, 2022). "We also found a higher proportion of isolated anti-Ro52/TRIM21 in patients with malignancy, consistent with previous studies." (PMID 35871174, 2022). "Recently, TRIM21- knockout mice were identified to be resistant to DEN-induced hepatocarcinogenesis because the genetic ablation of TRIM21 protected cancer cells from oxidative hepatic damage." (PMID 36261847, 2022). "What’s more, the crosstalk of TRIM21 in immunity and cancer therapy needs more research to be clarified." (PMID 36159815, 2022). "Our findings demonstrate that TRIM21 suppresses CHK1 activation by preferentially targeting CLASPIN for K63-linked ubiquitination, providing a potential target for cancer therapy." (PMID 35048968, 2022). "Growing evidence has shown that TRIM21 is also involved in the progression of human cancers: low TRIM21 expression was correlated with poor overall and disease-free survival in two independent cohorts, accounting for 1219 BC patients." (PMID 32781535, 2020). "Major functional components of this network (TNF, MAPK, TRIM21 and APP) were associated with metabolism and cancer." (PMID 32228434, 2020). "This network was composed of central functional components associated with metabolism and cancer such as TNF, MAPK, TRIM21 and one component contained APP." (PMID 32228434, 2020). "Several reports have shown the involvement of TRIM21 in cancer development, a characteristic shared by other TRIM family members and, interestingly, by endoglin." (PMID 31540324, 2019). "TRIM21 is a RING-finger domain-containing ubiquitin E3 ligase that plays an important role in cancer progress." (PMID 30886235, 2019). "To further clarify whether EPHX1 can counteract the pro‐cancer effects of TRIM21, we co‐expressed HIS‐EPHX1 and FLAG‐TRIM21 in BXPC3 and SW1990 cell lines." (PMID 39739616, 2025). "It is reported that TRIM21 plays diverse roles in different cancers through its E3 ligase activity." (PMID 40998798, 2025).